NPAT (nuclear protein, coactivator of histone transcription)
Description:
Transcription regulator required for progression through the G1 and S phases of the cell cycle and for S phase entry. Acts as a key transcription regulator of histones. Activates transcription of the histone H2A, histone H2B, histone H3 and histone H4 genes in conjunction with GON4L and MIZF. Together with CRAMP1, binds to the promoters of H1 genes (H1-2, H1-3, H1-4, H1-5 and H1-10/H1x), driving their transcription. Also positively regulates the ATM, MIZF and PRKDC promoters. Transcriptional activation may be accomplished at least in part by the recruitment of the NuA4 histone acetyltransferase (HAT) complex to target gene promoters.
Synonyms: E14; p220; E14/NPAT
Tractability: PROTAC: UniProt records ubiquitination sites on it; ubiquitination databases record sites on it.
Gene: Protein-coding gene on chromosome 11 (108,155,280 to 108,222,638, reverse strand). Ensembl gene ENSG00000149308.
Subcellular location: Nucleus; Nucleus, Cajal body; Chromosome
Subcellular location (Human Protein Atlas): Nuclear bodies; Nucleoplasm
Gene Ontology:
Molecular function: protein binding; transcription coactivator activity; transcription corepressor activity; transcription coregulator activity
Biological process: cell cycle G1/S phase transition; positive regulation of DNA-templated transcription; positive regulation of transcription by RNA polymerase II; negative regulation of DNA-templated transcription
Cellular component: Cajal body; chromosome; cytoplasm; Gemini of Cajal bodies; nuclear body; nucleoplasm; nucleus
Genetic constraint (gnomAD): Loss-of-function variants: 36 observed, 100.29 expected, observed/expected ratio (o/e) 0.36, 90% interval 0.27 to 0.47. The upper end of that interval is the gene's LOEUF score, 0.47, which puts it in group 2 of 6, group 1 being the genes least tolerant of losing a copy. Missense variants: 1,472 observed, 1,501 expected, observed/expected ratio (o/e) 0.98, 90% interval 0.94 to 1.02. Synonymous variants: 520 observed, 541.7 expected, observed/expected ratio (o/e) 0.96, 90% interval 0.89 to 1.03.
Homologues: Orthologues: chimpanzee NPAT (99% identical), macaque NPAT (97% identical), pig NPAT (83% identical), dog NPAT (78% identical), guinea pig NPAT (77% identical), mouse Npat (75% identical), rat Npat (74% identical), tropical clawed frog npat (34% identical), zebrafish npat (29% identical).
Diseases named in the same sentence as NPAT in open-access papers:
NPAT is named in the same sentence as 15 diseases in open-access papers, as found by Europe PMC text mining. Sharing a sentence is not in itself a finding about the gene and the disease. The quoted sentences say what the papers report.
breast carcinoma (7 papers, 2015 to 2025). "In the case of breast cancer, NPAT is found to associate highly with CDK2, which permits the overexpression of canonical histones during and outside of S-phase." (PMID 40996104, 2025). "Cyclin E2 uniquely interacts with NPAT in breast cancer cells, and is associated with higher levels of histones in breast cancer." (PMID 25741376, 2015). "The strongest association with breast cancer risk among BRCA1 carriers was observed for rs6589007, located at 11q22.3 in intron 15 of the NPAT gene (p = 4.6 × 10−3) at approximately 54 kb upstream of the ATM gene." (PMID 27796716, 2017). "In 526 breast cancers, high CCNE2 expression is associated with high levels of replication-dependent histones that are under the control of NPAT." (PMID 25741376, 2015). "Our observation of a specific NPAT-cyclin E2 interaction in breast cancer cell lines was supported by our findings of high expression of replication-dependent histones in breast cancers that have high expression of cyclin E2." (PMID 25741376, 2015). "We found by immunofluorescence that cyclin E2 co-localised with the major HLB protein, NPAT, in T-47D and MCF-7 breast cancer cells, but NPAT rarely co-localised with cyclin E1." (PMID 25741376, 2015). "Our re-examination of cyclin E function has identified that cyclin E2 is likely to have particular role in histone regulation in breast cancer via its unique interaction with NPAT." (PMID 25741376, 2015). "Likewise, impaired function of the upstream transcription factor NPAT has also been demonstrated in a variety of aggressive cancers, including Hodgkin’s lymphoma, colorectal cancers, and breast cancers." (PMID 40996104, 2025). "Exosomal miR-20a-5p is released by breast cancer cells and transferred to CD8+ T cells, where it inhibits their function by targeting the nuclear protein coactivator of histone transcription (NPAT)." (PMID 38994350, 2024).
Hodgkins lymphoma (4 papers, 2017 to 2025). A heterogeneous group of malignant lymphoid neoplasms of B-cell origin characterized histologically by the presence of Hodgkin and Reed-Sternberg (HRS) cells in the vast majority of cases. "NPAT germline mutations have been associated with Hodgkin lymphoma." (PMID 27796716, 2017). "For example, NPAT has been shown to undergo a truncated deletion in Nodular lymphocyte predominant Hodgkin lymphoma (NLPHL) and this mutation can serve as a candidate risk factor for Hodgkin lymphoma." (PMID 31598701, 2019).
ataxia telangiectasia (3 papers, 2011 to 2020). Ataxia-telangiectasia is the association of severe combined immunodeficiency (affecting mainly the humoral immune response) with progressive cerebellar ataxia. "The mammalian nuclear protein ataxia-telangiectasia (NPAT) gene, encoded by the responsible gene for ataxia telangiectasia, is a functional Mxc orthologue." (PMID 32111032, 2020). "The last, NPAT gene, encodes the nuclear protein of the ataxia telangiectasia mutated locus." (PMID 21859473, 2011). "Among these genes, NPAT and ATM genes are associated with ataxia telangiectasia, one of the most frequent autosomal recessive cerebellar ataxias." (PMID 23977206, 2013). "This region contains the NPAT and ATM genes associated with ataxia telangiectasia characterized by language impairment; the CUL5 (culin 5) gene in the same region may modulate the neuronal migration process related to language functions." (PMID 23977206, 2013).
leukemia (1 paper, 2020). A malignant (clonal) hematologic disorder, involving hematopoietic stem cells and characterized by the presence of primitive or atypical myeloid or lymphoid cells in the bone marrow and the blood. "Our findings in the Drosophila leukemia model will enable us to consider a similar involvement of NPAT, the human counterpart of Mxc, in the pathogenesis and development of leukemia." (PMID 32111032, 2020). "Our findings in the Drosophila model will enable us to consider a similar involvement of NPAT, the human counterpart of Mxc, in the pathogenesis and development of leukemia." (PMID 32111032, 2020).
mental retardation (1 paper, 2022). "Chromosomal microarray analysis (CMA) studies, where the copy number variants (CNVs) containing the NPAT locus have been categorized as the pathogenic events for mental retardation, implicate NPAT as a candidate disease gene." (PMID 35642004, 2022). "How a “tumor suppressor” NPAT, when its function is defective, leads to human mental retardation remains a key question." (PMID 35642004, 2022). "NPAT, a component of the histone locus body (HLB), has been implicated as a candidate gene for mental retardation, with a mechanism yet to be elucidated." (PMID 35642004, 2022). "Although NPAT gene has been reported as a candidate gene for mental retardation, no genetic mutations of NPAT gene have been found in clinic cases." (PMID 35642004, 2022). "However, no point mutations within NPAT gene have yet been reported in mental retardation cases and any potentially related pathogenic mechanisms remain to be elucidated." (PMID 35642004, 2022).
type 2 diabetes (1 paper, 2021). "The NPAT gene lies within a genetic locus that associates with metformin response in humans with type 2 diabetes." (PMID 34197485, 2021).
cancer (8 papers, 2014 to 2026). A tumor composed of atypical neoplastic, often pleomorphic cells that invade other tissues. "Other transcription factors are associated with cancer-related pathways, such as NPAT, ZNF264, HEYL and ETV4." (PMID 33525507, 2021). "Many regulators including CBP/p300, ATAD2, Cyclin E2, SWI/SNF and NPAT play important roles in cancer survival and proliferation." (PMID 29212286, 2017). "CDK2 is the kinase that phosphorylates Mxc/NPAT for histone gene activation, linking conserved HLB regulation described here to a deeper understanding of cancer." (PMID 41491041, 2026).
tumor (1 paper, 2021). "In contrast to tumors, the adjacent non-tumor tissues harbored eight genes with recurrent HBV integration, including FN1, DCC, OAZ2, ANO3, ENOX1, GRIK4, NPAT, and SNCAIP." (PMID 34209079, 2021).
NPAT also shares sentences with these, for which no sentence is quoted: asthma (1 paper); autosomal recessive cerebellar ataxia (1); glioma (1); infection (1); lung adenocarcinoma (1); lung carcinoma (1); Telangiectasia (1).